MALAT1 (metastasis associated lung adenocarcinoma transcript 1)
Diseases named in the same sentence as MALAT1 in open-access papers (continued):
Sharing a sentence is not in itself a finding about the gene and the disease.
cancer (continued). "Our analysis identified numerous SIR-associated mutations in oncogenes (e.g., MECOM, NFATC2) and tumor suppressor genes (e.g., LRP1B, PTPRD), as well as in cancer-associated lncRNAs (e.g., MALAT1, NEAT1)." (PMID 41153425, 2025). "In fibroblasts cocultured with endothelial cells, we observed significant upregulation of genes associated with cancer progression (MALAT1, NEAT1), vascular endothelial growth factor (VEGFA), and proinflammatory cytokines (NCOA3, IRF1)." (PMID 39805002, 2025). "MALAT1, or as Alpha on chromosome 11q13 was one of the first long non‐coding RNAs (lncRNAs) identified to be associated with cancer." (PMID 40783798, 2025). "We chose MALAT1 as the candidate for further study as it has been previously shown to be upregulated in various cancers and associated with cancer progression." (PMID 38639382, 2024). "MALAT1 has been identified as a key oncogene, with its increased expression linked to cancer advancement and unfavorable outcomes in CRC." (PMID 39830506, 2024). "Studies of cancer tissue have shown that the increased expression of MALAT1 is associated with poorer prognosis in CRC patients." (PMID 39471147, 2024). "Subsequent studies found a variety of associations between Malat1 and the growth and metastasis of different cancers, such as lung cancer, hepatocellular carcinoma, and breast cancer." (PMID 39714456, 2024). "The role of lncRNA MALAT1 in cancer-associated cachexia through inhibition of adipogenesis via regulation of PPARγ has also been reported." (PMID 39199690, 2024). "Ultimately, the in-depth investigation of MALAT-1 has shown its important pathogenic molecular function in cancer, including many carcinogenesis phases and the emergence of chemoresistance." (PMID 38511067, 2024). "Among the trans-acting lncRNAs detected, we observed the presence of MALAT1, a cancer-related lncRNA previously implicated in metastasis, chromatin association and modulation." (PMID 38942785, 2024). "The association of the MALAT1 rs3200401 variant with cancer risk has been extensively investigated in recent years." (PMID 38390896, 2024). "From the figure, it is revealed that the high expression of MALAT1 [HR(high) < 1] is associated with better survival in cancer patients." (PMID 39725668, 2024). "It has been reported that miR-9 exerts regulatory functions within the nucleus by targeting the lncRNA MALAT1 (metastasis-associated lung adenocarcinoma transcript 1), which plays a role in cancer progression (right)." (PMID 38473229, 2024). "For instance, the cancer-associated nuclear lncRNA MALAT-1 has been reported as a target of miR-9, while another cancer-associated nuclear lncRNA, XIST, has been reported as a target of miR-210." (PMID 38167929, 2024). "This study offers a comprehensive examination of the pathogenic molecular function of MALAT-1 in cancer, focusing on its role in promoting carcinogenesis and the development of chemoresistance." (PMID 38511067, 2024). "Another lncRNA, MALAT1, has been linked to the promotion of cell proliferation and inhibition of apoptosis in various cancer types." (PMID 39257589, 2024). "MALAT1 (Metastasis Associated Lung Adenocarcinoma Transcript 1) is a widely recognized Long non-coding RNA (lncRNA) in cancer." (PMID 38753424, 2024). "Recent findings show that MALAT-1 influences several immune cells implicated in cancer immunity in addition to its function in cancer cell biology." (PMID 38511067, 2024). "MALAT1 was upregulated in different cancers and has been associated with tumor progression, invasion, and chemoresistance." (PMID 39170516, 2024). "In summary, our knowledge of the intricate regulatory networks involved in carcinogenesis and treatment response has increased due to our developing comprehension of the pathogenic molecular function of MALAT-1 in cancer." (PMID 38511067, 2024). "Alterations in MALAT1 expression and/or function have been associated with different types of cancer." (PMID 38791553, 2024).
cancer (continued). "We also found that the MUC1-C/XIST pathway regulates expression of the NEAT1 and MALAT1 lncRNAs, which have been linked to inflammation and cancer progression." (PMID 38740827, 2024). "Another study found that, in combination with the translation process of lncRNA MALAT1 as well as its manifestation in cancer cells, the association between lncRNA-MALAT1 polymorphisms and carcinogenesis should be revealed." (PMID 39346921, 2024). "MALAT1 (metastasis-associated lung adenocarcinoma transcript 1) is one of the first identified cancer-associated long noncoding RNAs." (PMID 38696425, 2024). "Among the hub genes of subtype II, MALAT1 has been identified as intimately linked to the development, progression, and metastasis of various human cancers." (PMID 39336798, 2024). "The acquisition of characteristics resembling cancer stem cells has also been linked to MALAT-1 deregulation, which adds to tumor heterogeneity and therapeutic resistance." (PMID 38511067, 2024). "As shown here, MALAT-1 plays a cancer-causing function in GC by facilitating cancer cell proliferation, migration, and invasion." (PMID 38511067, 2024). "Overall, unraveling the complex molecular mechanisms underlying the pathogenic role of MALAT-1 in cancer will deepen our understanding of tumor biology and hold great promise for developing novel diagnostic tools and therapeutic strategies." (PMID 38511067, 2024). "Further research is required to examine the diagnostic and prognostic use of MALAT-1 in various cancer types and stages." (PMID 38511067, 2024). "Metastasis-associated lung adenocarcinoma transcript 1 (MALAT1) is a highly conserved lncRNA implicated in various physiological and pathological processes, including cancer, cardiovascular diseases, and neurological disorders." (PMID 39682691, 2024). "Although previous reports observed a link between Malat1 and β-catenin signaling pathway in cancers 34,35, the underlying molecular mechanisms were unclear." (PMID 38234849, 2024). "Metastasis-associated lung adenocarcinoma transcript 1 (MALAT-1) influences crucial cancer hallmarks through intricate molecular mechanisms, including proliferation, invasion, angiogenesis, apoptosis, and the epithelial-mesenchymal transition (EMT)." (PMID 38511067, 2024). "Aberrant expression of MALAT1 is associated with metastasis in multiple types of cancers, and MALAT1 can act as a metastasis promoter or metastasis suppressor depending on the cancer type." (PMID 38540273, 2024). "It is well known that Myc, Sp1, BMI1, and MALAT1 are cancer stem cell (CSC) markers implicated in chemoresistance in NSCLC." (PMID 38125755, 2024). "Metastatic-associated lung adenocarcinoma transcript 1 (MALAT1) is a widely studied long noncoding RNA (lncRNA) known for its significant role in oncogenesis and cancer progression." (PMID 39335515, 2024). "Subsequent studies found a variety of associations between Malat1 and the growth and metastasis of different cancers, such as lung cancer, hepatocellular carcinoma, and breast cancer 15,16." (PMID 38234849, 2024). "In recent years, studies have also revealed that genetic polymorphisms of MALAT1 have susceptibility to cancers." (PMID 38517388, 2024). "For instance, miR-34a, a well-studied tumor suppressor, has shown therapeutic potential in various cancers, LncRNAs, such as HOTAIR and MALAT1, are associated with cancer progression and metastasis." (PMID 39415281, 2024). "The artificial anchoring of YTHDC1 to m6A-deficient MALAT1 notably rescues the metastatic potential of cancer cells." (PMID 38255219, 2024). "Although previous reports observed a link between Malat1 and β-catenin signaling pathway in cancers, the underlying molecular mechanisms were unclear." (PMID 39714456, 2024). "MALAT-1 appears as a possible diagnostic biomarker, therapeutic target, and prognostic indication in several cancer types." (PMID 38511067, 2024).
cancer (continued). "In the miRNA–overexpressing cells, we discovered a convergent dysregulation of genes linked to apoptosis, ATP synthesis, angiogenesis, and cancer progression, including a long non–coding RNA associated with oncogenesis, i.e., MALAT1." (PMID 38339342, 2024). "Metastasis-associated lung adenocarcinoma transcript 1 (MALAT1) is a lncRNA that is upregulated in various cancers, such as breast, pancreatic, lung, colon, prostate, liver, and bladder." (PMID 36605618, 2023). "OM-resistant cancer cells showed a high level of MALAT1 expression, and this was associated with poor survival." (PMID 38136198, 2023). "It is believed that MALAT-1 has been implicated in cancer cell migration, invasion, tumor progression, and metastasis in RCC." (PMID 38124072, 2023). "Nevertheless, this study can give a better understanding of how MALAT1 acts in NSCLC and contribute to the identification of cancer-associated signaling pathways regulated by MALAT1." (PMID 37667226, 2023). "Metastasis-associated lung cancer transcript 1 (MALAT1) is closely associated with the occurrence and development of various human cancers." (PMID 36903369, 2023). "MALAT-1 has been associated with resistance to chemotherapy and targeted therapies in various cancer types." (PMID 38124072, 2023). "Metastasis Associated Lung Adenocarcinoma Transcript 1 (MALAT1) is an evolutionally conserved long non-coding RNA, implicated in various cancer and inflammatory diseases." (PMID 37398640, 2023). "MALAT-1 has been implicated in various biological processes and has emerged as a key player in cancer development and progression." (PMID 38124072, 2023). "A study indicated that elevated miRNA-182-5p was associated with cancer cells’ mitotic arrest through MALAT1 expression." (PMID 37251950, 2023). "Among the thirty MALAT1 targets commonly found in the small intestine and colon, many have been previously implicated in other types of cancers." (PMID 37325561, 2023). "MALAT-1 (Metastasis-Associated Lung Adenocarcinoma Transcript 1) is a lncRNA that has been extensively studied in various cancers, including lung, colon, breast, ovary, gastric, bladder, and hepatic." (PMID 38124072, 2023). "Metastasis-associated lung adenocarcinoma transcript 1 (MALAT1) is a lncRNA connected with cancer angiogenesis." (PMID 37046644, 2023). "Another highly conserved lncRNA, metastasis associated lung adenocarcinoma transcript 1 (MALAT1) regulates the expression of genes via modulating transcription and post‐transcriptional RNA processing in various cancers." (PMID 37795578, 2023). "MALAT1 (Metastasis-Associated Lung Adenocarcinoma Transcript 1) was one of the first lncRNAs described to be associated with cancer." (PMID 37370745, 2023). "It is reported that the abnormal MALAT1 expression is closely associated with the chemoresistance of different cancers." (PMID 36793374, 2023). "For example, the lncRNA MALAT1 (metastasis-associated lung adenocarcinoma transcript 1) is overexpressed in various types of cancer and involved in cancer cell proliferation, migration, and invasion via promoting the expression of oncogenes such as TGF-β1." (PMID 37232821, 2023). "The long non-coding RNA metastasis-associated lung adenocarcinoma transcript 1 (MALAT1) is a cancer biomarker." (PMID 37165307, 2023). "MALAT1 is another one of the most frequently studied ncRNAs, and its upregulation is associated with a low survival rate in different cancers." (PMID 36726376, 2023). "MALAT1 has emerged as a metastasis-associated lncRNA in multiple malignancies and serves as a predictor in assessing response to cancer therapies." (PMID 37812088, 2023). "Abnormal expression of MALAT1 has been reported to be associated with the occurrence, progression, metastasis and chemotherapy resistance of cancers." (PMID 36829256, 2023). "Among the most prominent examples of lncRNAs whose aberrant expression is associated with cancer development are the descriptions of MALAT1, HOTAIR, and PCA3." (PMID 38068923, 2023).
cancer (continued). "Metastasis associated lung adenocarcinoma transcript 1(MALAT1) is a ubiquitous lncRNA in mammals, it is widely explored in cancer and crucial for the regulation of cancer-related pathways." (PMID 37805491, 2023). "MALAT1 is an evolutionally conserved long non-coding RNA, implicated in various cancer and inflammatory diseases." (PMID 37398640, 2023). "Targeting of these genes by miR-15/16 is consistent with their known tumor suppressor role and with Malat1’s association with cancer cell proliferation and metastasis, providing new mechanistic insight into those observations." (PMID 38127070, 2023). "Metastasis-associated lung adenocarcinoma transcript 1 (MALAT1) overexpression has been found in various cancer cell lines and tumors." (PMID 36831169, 2023). "The lncRNA metastasis-associated lung cancer transcript 1 (MALAT1) is reportedly involved in the occurrence and development of many cancers and serves as a biomarker and therapeutic target." (PMID 36903369, 2023). "Metastasis-associated lung adenocarcinoma transcript 1 (MALAT1) is a widely studied lncRNA in cancer and is important for cancer-related pathway regulation." (PMID 36300115, 2022). "The well-known lncRNA Metastasis-associated lung adenocarcinoma transcript 1 (MALAT1) has also been identified in OC-EVs and it is associated with cancer angiogenesis and metastasis." (PMID 35884464, 2022). "Genetic variants of long noncoding RNA metastasis-associated lung adenocarcinoma transcript 1 (lncRNA MALAT1) have been reported to be associated with several cancers." (PMID 35517413, 2022). "Background and Objectives: At present, the association between the long non-coding RNA (lncRNA) metastasis-associated lung adenocarcinoma transcript 1 (MALAT1) polymorphism rs3200401 C > T and cancer risk remain controversial." (PMID 35208500, 2022). "The long non-coding RNA (lncRNA), MALAT1, plays a key role in the development of different cancers, and its expression is associated with worse prognosis in patients." (PMID 35016717, 2022). "High expression of MALAT1 was associated with a significant reduction in cancer-specific survival (χ2 = 12.39, p = 0.0004) over a 14-year timing, when compared to patients with low MALAT1 expression." (PMID 35016717, 2022). "Metastasis-associated lung adenocarcinoma transcript 1 (MALAT1) is a long noncoding RNA (lncRNA) highly expressed in several cancers types and is associated with many aspects of cancer progression." (PMID 35557985, 2022). "MALAT1 is one such lncRNA whose elevated levels are seen in numerous human cancers and is associated with poor prognosis in several human malignancies." (PMID 36230680, 2022). "Metastasis associated in lung adenocarcinoma transcript 1 (MALAT1) is considered as one of the most studied lncRNAs in cancer and is also known as nuclear enrichment autosomal transcript 2 (NEAT2)." (PMID 36387279, 2022). "Some studies explored the role of metastasis-associated lung adenocarcinoma transcript 1 (MALAT1) in cancer." (PMID 35769097, 2022). "Metastasis-associated lung adenocarcinoma transcript 1 (MALAT1) was initially found to regulate cancer metastasis." (PMID 36117707, 2022). "Among all the cancer associated long non-coding genes reported (, Lnc2Cancer v3.0), we identified mutations of MALAT1, HOTAIR and ZFAS1 in these cell line models." (PMID 36153537, 2022). "Although the function of MALAT1 has been widely reported in cancer, the underlying mechanisms in PCa are yet to be elucidated." (PMID 35557985, 2022). "For instance, MALAT1 (metastasis-associated lung adenocarcinoma transcript 1) is a cancer-related lncRNA that has been frequently observed." (PMID 35159299, 2022). "Larger sample size studies on a wide range of cancer types are required to perform further verification about the relationship between MALAT1 polymorphism rs3200401 and cancer risk." (PMID 35208500, 2022).
cancer (continued). "Metastasis-associated lung adenocarcinoma transcript 1 (MALAT1), one of the first lncRNAs reported to be involved in cancer metastasis, is aberrantly expressed in multiple human malignancies and can act as a sponge for various miRNAs." (PMID 36172152, 2022). "Although associated with several aspects of cancer progression, the function and mechanism of MALAT1 in PCa need to be explored further." (PMID 35557985, 2022). "The metastasis-associated lung adenocarcinoma transcript 1 (MALAT1) is localized in the nuclear speckle periphery and it is widely studied in cancer development and progression." (PMID 35978835, 2022). "SNPs have been extensively studied as biomarkers, and the association between MALAT1 polymorphism rs3200401 C > T and cancer risk has been investigated in recent years." (PMID 35208500, 2022). "This MALAT1-GLI1 fusion mutation activated Hh signaling and consequently led to malignant tumor formation, suggesting a relationship between MALAT1 function and Hh signaling activity." (PMID 36084949, 2022). "Recently, many studies have focused on the relationship between genetic variation in MALAT1 and cancer risk." (PMID 35208500, 2022). "LncRNA MALAT1, as one of the classical lncRNAs associated with tumours, is highly expressed in many cancer types." (PMID 34750493, 2022). "LncRNA metastasis associated lung adenocarcinoma transcript 1 (MALAT1) has been known to be correlated with tumor metastasis in human cancer." (PMID 35928868, 2022). "Plasma levels of H19 in breast cancer, and H19, HOTAIR, and MALAT1 in gastric cancer have shown high diagnostic potential, while single nucleotide polymorphisms in the H19 gene have applications in cancer risk prediction." (PMID 35892331, 2022). "LncRNA MALAT1 (metastasis-associated lung adenocarcinoma transcript 1) expression was shown to be upregulated in several types of cancer, including BC, where it can induce migration and stimulate the growth of cancer cells." (PMID 35865634, 2022). "The highly conserved MALAT1 attracted the attention of researchers, and a series of studies have shown that MALAT1 was associated closely with tumor proliferation and invasion by interacting with several famous cancer-related signaling pathways." (PMID 35433477, 2022). "MALAT1 rs3200401 C > T polymorphism has also been extensively studied in relation to different cancer risks." (PMID 35208500, 2022). "A well-studied lncRNA metastasis associated lung adenocarcinoma transcript 1 (MALAT1) exerts crucial functions in numerous disorders such as cancers." (PMID 35813614, 2022). "LncRNA MALAT1, also known as NEAT2, is highly expressed in cancer and mainly associated with tumor cell proliferation, apoptosis, migration, invasion, and functions as ceRNA." (PMID 35573984, 2022). "The JQ1-caused up-regulation of MALAT1 appears paradoxical because BET inhibitors are being considered as anti-cancer agents." (PMID 35546353, 2022). "Metastasis-associated lung adenocarcinoma transcript 1 (MALAT1), a prominent intergenic long noncoding RNA (lncRNA), is well known for its role in influencing epigenetic mechanisms in cancer." (PMID 36397159, 2022). "TGF-β1 induces the LncRNA MALAT-1 (metastasis-associated lung adenocarcinoma transcript 1) in several types of cancer to promote EMT via different downstream mechanisms." (PMID 35736633, 2022). "MALAT1 (Metastasis Associated Lung Adenocarcinoma Transcript 1) is a lncRNA highly expressed by several types of cancers and associated to cancer progression and worse prognosis in cancer patients." (PMID 35016717, 2022). "Metastasis Associated Lung Adenocarcinoma Transcript 1 (MALAT-1) is the most well-characterized lncRNA linked to lung cancer metastasis; it regulates cancer development by functioning as a competing endogenous RNA (ceRNA) to sponge a series of miRNAs." (PMID 34692550, 2021).